POMC (proopiomelanocortin)
Diseases named in the same sentence as POMC in open-access papers (continued):
Sharing a sentence is not in itself a finding about the gene and the disease.
melanoma (continued). "This study has first demonstrated that POMC gene therapy simultaneously induces two different types of cell death: autophagy and apoptosis in melanoma in vivo." (PMID 30062060, 2018). "The similar results also were obtained by POMC gene delivery in B16-F10 melanoma cells (Supplementary 1A-C)." (PMID 30062060, 2018). "In recent years, we have demonstrated the anti-angiogenic potential of POMC therapy in pre-clinical animal models of diseases due to excessive angiogenesis such as B16-F10 melanoma, Lewis lung carcinoma, and osteoarthritis." (PMID 30513637, 2018). "Systemic proopiomelanocortin (POMC) gene therapy suppresses melanoma through apoptosis induction and neovascularization blockage." (PMID 30062060, 2018). "However, because of the pleiotropic properties of POMC-derived peptides, including their direct or indirect immunosuppressive effects, when this system is deregulated during melanoma progression it can negatively affect the disease outcome." (PMID 38927967, 2024). "Thus, the local POMC signaling system with its upstream and downstream regulatory pathways can represent a target either for melanoma prevention or adjuvant therapy in a context dependent fashion." (PMID 38927967, 2024). "However, POMC overexpression reduces the melanoma growth by apoptosis and autophagy via complex α-MSH-HIF-1 α/BCL2 and adenovirus E1B 19-kDa-interacting protein 3 (BNIP3) signalling pathways." (PMID 35334544, 2022). "Moreover, UV-B exposure of melanoma cells increases the transcription of POMC mRNA, the production of POMC and ACTH, and also the expression of MSH receptors, most likely through a cAMP-dependent pathway." (PMID 34068618, 2021). "Moreover, it was shown that autophagy is involved in promoting cell death in POMC-mediated melanoma suppression through the α-MSH/hypoxia-inducible factor-1α/BNIP3/BNIP3L signaling pathway." (PMID 34068618, 2021). "Furthermore, in melanoma cell culture CRH induced the expression of POMC mRNA, while a CRH antagonist suppressed it." (PMID 34068618, 2021). "Therefore, the present study unveils that POMC therapy induces the activation of autophagic and apoptotic cell death pathways in melanoma cells through α-MSH/HIF-1α/BNIP3 signaling." (PMID 30062060, 2018). "Subsequently, we investigated whether POMC gene delivery could enhance the autophagy in B16-F10 melanoma cells." (PMID 30062060, 2018). "Therefore, the present study unveiled a unique function of autophagy in promoting cell death during POMC-mediated melanoma suppression via α-MSH/HIF-1α/BNIP3/BNIP3L signaling pathway." (PMID 30062060, 2018). "Such autophagy induction could be recapitulated in melanoma cells receiving POMC gene delivery and hypoxia-mimicking agent cobalt chloride (CoCl2)." (PMID 30062060, 2018). "However, the mechanisms of POMC-induced apoptosis in melanoma cells under hypoxic condition is still notenough comprehension." (PMID 30062060, 2018). "MC1R is a G protein-coupled receptor (GPCR) expressed in melanocytes and melanoma cells, whose activity is positively regulated by the peptide agonists α-melanocyte-stimulating hormone (αMSH) and adrenocorticotropin, derived from the precursor polyprotein proopiomelanocortin." (PMID 37762683, 2023). "The highly conserved interactions between the MCH and melanocortin pathways in controlling the development and function of melanocytes introduces the possibility that MCH variants might also be risk factors for melanoma, whereby changes in MCH affect POMC/α-MSH signaling." (PMID 33301440, 2020). "Other POMC-derived peptides, such as α-MSH and melanocortin 1 receptor (MC1R) are also expressed in melanoma cell lines, nodular and metastatic melanoma." (PMID 34068618, 2021). "Another secreted protein, proopiomelanocortin (POMC), is a precursor peptide that gives rise to multiple derivative peptides such as α-MSH, a known promoter of the growth and metastasis of melanoma." (PMID 24743777, 2014).
melanoma (continued). "Circulating anti-POMC antibodies in the serum were identified both in a previously reported case of spontaneous IAD with LCNEC and in patients who had ICI-related hypophysitis diagnosed with malignant melanoma or renal cell carcinoma." (PMID 38035072, 2023). "Ectopic ACTH expression in tumor tissues and circulating anti-POMC antibodies in the serum have also been identified in a subset of patients with ICI-related hypophysitis diagnosed with malignant melanoma or renal cell carcinoma." (PMID 38035072, 2023). "Meanwhile, the human melanoma line, which is shown to express CYP17, CYP21A2, POMC and CRH genes, could metabolize progesterone to corticosterone." (PMID 33529200, 2021). "Consistently, our previous studies have demonstrated that the gene delivery of proopiomelanocortin (POMC), the precursor of alpha-melanocyte stimulating hormone (α-MSH), effectively suppresses the progression and metastasis of melanoma though the inhibition of COX-2/PGE2 signaling." (PMID 31968661, 2020). "Melanomas produce higher levels of LIF and POMC, suggesting LIF may stimulate melanoma growth in part by promoting HPA axis peptides." (PMID 26329521, 2015). "Moreover, the coordinated activity of the CRH-POMC axis was demonstrated in both primary and metastatic melanoma, colocalization of CRH and POMC peptides being emphasized in the great majority of CRH positive melanomas." (PMID 34068618, 2021). "Since the inhibition of NFκB/COX-2 signaling is involved in POMC-mediated melanoma suppression, we elucidated whether MTII also perturbed COX-2 expression as well as prostaglandin E2 (PGE2) secretion in B16-F10 melanoma cells." (PMID 31968661, 2020).
hypophysitis (61 papers, 2012 to 2025). Inflammation of the pituitary gland. "In a study analyzing 20 patients with PD-1/PDL-1-related hypophysitis who experienced isolated ACTH deficiency, circulating anti-proopiomelanocortin (POMC) antibodies were detected in approximately 10% of cases." (PMID 39941803, 2025). "Considering that ACTH deficiency is the most common endocrine abnormality reported in patients with hypophysitis POMC is an attractive candidate autoantigen." (PMID 37623461, 2023). "Growth hormone and proopiomelanocortin were also suggested as antigens of IgG4-related hypophysitis." (PMID 34683167, 2021). "Immune−mediated mechanisms, including ectopic POMC expression and autoimmunity against corticotrophs, have been implicated in ICI−induced hypophysitis and may underlie these molecular changes." (PMID 41189622, 2025). "However, further investigation is necessary to determine whether the location of the POMC recognized by autoimmune antibodies in the patient’s serum is consistent with that of other cases of paraneoplastic ACTH deficiency and ICI-related hypophysitis." (PMID 38035072, 2023).
Anorexia (58 papers, 2009 to 2026). Lack of desire to eat (loss of appetite). "For instance, in the hypothalamus, a brain region that controls food intake, TNFα inhibits orexigenic AgRP neurons and activates anorexigenic proopiomelanocortin (POMC) neurons, promoting inflammation-associated anorexia." (PMID 39958993, 2025). "Inflammatory cytokines IL-18 and IL-6 can further activate the NF-κB signaling pathway, regulating POMC activity to cause anorexia." (PMID 39691381, 2024). "Animals deficient for POMC are obese, while ablation of AgRP neurons in adult mice leads to anorexia and leanness, highlighting the importance of POMC and AgRP neurons in regulating energy homeostasis." (PMID 38027481, 2023). "Chronic stress results in reduced body weight and anorexia that is associated with increased ARC POMC neuron activity." (PMID 33250721, 2020). "Infection-related anorexia and weight loss are mediated via NF-κB activation in hypothalamic pro-opiomelanocortin (POMC) neurons." (PMID 23637966, 2013). "In addition, we further found that central administration of visfatin led to anorexia and body weight loss, at least in part, via promoting the activity of proopiomelanocortin (POMC) neurons." (PMID 29362519, 2017). "On the other hand, the POMC transcript is increased in mice following activity-based anorexia, a rodent model of anorexia nervosa." (PMID 36831755, 2023). "In this study, we report that GALR2 is involved in SPX’s effects on leptin-induced anorexia and POMC expression." (PMID 35204737, 2022). "In this study, we found that central SPX induces anorexia and increases hypothalamic POMC mRNA expression." (PMID 35204737, 2022). "Both NPY/AgRP and POMC are important downstream targets of insulin, and one of the core roles of insulin is to produce anorexia by suppressing the NPY/AgRP neurons and stimulating POMC neurons." (PMID 33868169, 2021). "Acute inflammation activates POMC neurons, which increase melanocortin-4 receptor (MC4R) expression and POMC expression, as shown in the LPS- and IL-1β-induced anorexia model." (PMID 34899611, 2021). "The ROS with the strongest effect on POMC neurons seems to be H2O2, increasing H2O2 can cause depolarization of POMC neurons, and ICV injection of H2O2 can cause significant anorexia." (PMID 33763034, 2021). "In contrast, deletion of Trpc5 in all POMC neurons leads to an age-dependent increase in body weight, with increased food intake, decreased energy expenditure, and attenuated leptin-mediated anorexia, although glucose homeostasis was unchanged." (PMID 30304668, 2018). "They identified POMC as a potential mediator of illness-induced anorexia and as a possible downstream target of NF-κB." (PMID 28855891, 2017). "In rodent kidney disease, it has been shown that MC4R and POMC play a role in anorexia, modifying body composition, and this involves cytokines." (PMID 26734008, 2015). "These last reactions from orexigenic peptides tend to attenuate the anorexigenic effects of CART and POMC and by consequent to abolish the anorexia state generated by stress." (PMID 25100947, 2014). "Both neuropeptide Y (NPY) and proopiomelanocortin (POMC) are involved in regulating AMPH-induced anorexia." (PMID 24225225, 2013). "Increased cytokines in the hypothalamus enhance serotoninergic tone through tryptophan, resulting in activation of POMC neurons and subsequent anorexia." (PMID 22518191, 2012). "Our result of remarkable expression of c-Fos in ARC after ip injection of Oxt suggests that ip Oxt injection causes anorexia partly by activating anorectic neurons in ARC, including POMC neurons." (PMID 22184277, 2011). "One mechanism by which the cytokines (and other appetite regulating molecules such as leptin) can induce anorexia is via the regulation of pro-opiomelanocortin (POMC) expression." (PMID 19295909, 2009).
Anorexia (continued). "Concurrently, while the role of BDNF in promoting anorexia is still being fully elucidated, it appears that its signaling is both stimulated by and responsible for promoting POMC secretion, while also increasing energy expenditure through increased physical activity." (PMID 38019584, 2024). "DON-induced anorexia can indirectly affect appetite by inducing a significant release of peripheral satiety hormones, in addition to upregulating central anorexigenic molecules such as POMC and melanocortin 4 receptor (MC4R)." (PMID 39691381, 2024). "In goldfish, intraperitoneal injection of SPX induced anorexia, accompanied by an increase in hypothalamic expression of anorexigenic neuropeptide proopiomelanocortin (POMC), with a simultaneous decrease in orexigenic neuropeptide Y (NPY) and agouti-related peptide (AgRP)." (PMID 35204737, 2022). "One of the components influencing weight loss during immobilization stress, apparently, is the increased expression kinetics of anorexigenic (POMC and CART) and orexigenic (NPY and AgRP) peptides and, as a result, anorexia caused by a violation of the homeostatic circuit." (PMID 36558137, 2022). "Therefore, POMC is a potential mediator of illness-induced anorexia and a downstream target of NF-κB." (PMID 34899611, 2021). "This differential increased anorexia in UniNX animals compared to Sham animals may be explained by increases in anorexigenic hypothalamic neuropeptides POMC, CRF, and CART mRNA levels." (PMID 26734008, 2015). "POMC was also significantly increased during stress‐induced anorexia." (PMID 26017156, 2015). "In the limited number of studies where AgRP/NPY or POMC/CART have been measured in mammalian models of stress that result in anorexia, there is some evidence for increased expression of the orexigenic peptide genes but the significance of this finding is uncertain." (PMID 26017156, 2015). "Thus, the increase of DVC AgRP gene expression just after the termination of stress up to 24 h before POMC gene expression suggests that AgRP system drive the expression of the POMC to attenuate the ongoing established anorexia state." (PMID 25100947, 2014). "Thus, our results indicate that POMC may be the key regulatory factor in LPS-induced anorexia which was reflected in the decreased feed intake of broilers 72 h after LPS administration." (PMID 37207231, 2023). "Moreover, the RNA-seq data indicated that LCN2 affected gene expression in anorexigenic POMC neurons, which may have relevance in cachexia-anorexia, although POMC expression itself was unchanged." (PMID 35031523, 2022). "In the case of stress‐induced anorexia, increased POMC may contribute to this inhibitory role, whereas, for incubation, reduced feeding may also be associated with increased expression in the hypothalamus of the anorexigenic peptide vasoactive intestinal peptide." (PMID 26017156, 2015). "The mechanism for ACS is the increase in serotonin levels through the tryptophan pathway, responsible for activating proopiomelanocortin neurons (POMC), which were found to be involved in anorexia in tumor-bearing animals." (PMID 41373996, 2025). "Insulin can affect appetite by acting on hypothalamic neurons, promoting anorexia by decreasing NPY and stimulating POMC expression and through regulating ghrelin suppression." (PMID 28677623, 2017). "The other produces cocaine and amphetamine regulated transcript (CART) and proopiomelanocortin- (POMC-) derived peptides, such as alpha melanocyte stimulating hormone (αMSH), that promote anorexia by inhibiting food intake and increases catabolic processes." (PMID 24744782, 2014). "The other produces cocaine and amphetamine regulated transcript (CART) and proopiomelanocortin (POMC)-derived peptides, such as alpha melanocyte stimulating hormone (αMSH), that promote anorexia by inhibiting food intake and increasing catabolic processes." (PMID 24015235, 2013).
Anorexia (continued). "Activation of POMC/CART-expressing neurons by leptin results in release of α-MSH, which subsequently binds to melanocotin receptors (MCRs) and leads to anorexia and increased energy expenditure." (PMID 22518191, 2012). "Combined with previous findings, these data imply that LPS-induced anorexia may derive from the concerted action of NPY and POMC." (PMID 37207231, 2023). "Current research has confirmed that LIFR is expressed in proopiomelanocortin (POMC) neurons in the arcuate nucleus (ARC) region in the hypothalamus, which can be activated by LIF and then α-MSH released from ARC POMC neurons to induce anorexia." (PMID 35740622, 2022). "One study showed that stimulation of TLR2 by intracerebroventricular injection of the synthetic ligand Pam3CSK4 induced anorexia and increased IBA1-positive microglial density and structural contacts with proopiomelanocortin (POMC) neurons in the hypothalamic arcuate nucleus of mice." (PMID 29354029, 2017). "However, the majority of 5-HT2CRNTS are not found on POMC neurons, thus other NTS neuron populations could also contribute to lorcaserin anorexia from the NTS." (PMID 36592795, 2023).
Sepsis (57 papers, 2009 to 2026). Sepsis is defined as life-threatening organ dysfunction caused by a dysregulated host response to infection. "In consideration of these results, it seems reasonable to speculate that changed POMC expression is also implicated in the impairment of hepatic GNG in the context of sepsis." (PMID 29285858, 2018). "PC1/3, responsible for proteolytic cleavage and processing of POMC into ACTH, was acutely and persistently downregulated at both the gene and the protein level during sepsis-induced critical illness (all p < 0.01)." (PMID 33593393, 2021). "The first important and novel finding was the high levels of circulating POMC in both the acute and prolonged human sepsis studies as well as in the mouse model of sepsis." (PMID 33593393, 2021). "In two human studies of acute (ICU admission to day 7, N = 71) and prolonged (from ICU day 7 until recovery; N = 65) sepsis-induced critical illness, POMC plasma concentrations were quantified in relation to plasma ACTH and cortisol." (PMID 33593393, 2021). "The two human studies revealed several-fold elevated plasma concentrations of the ACTH precursor POMC from the acute to the prolonged phase of sepsis and upon recovery (all p < 0.0001), coinciding with the known ACTH–cortisol dissociation." (PMID 33593393, 2021). "With regard to the impact of POMC knockdown on hepatic GNG in sepsis rats, we next measured expression of STAT3 and key enzymes involved in GNG via Western blot or quantitive PCR analysis." (PMID 29285858, 2018). "Collectively, these results suggested a POMC‐depended effect of insulin on restoring hepatic GNG in sepsis rats." (PMID 29285858, 2018). "In summary, our work shows that insulin administration displays critical liver and glucose metabolism protective roles in sepsis rat models, possibly through suppression of NF‐κB pathway and neuropeptide POMC‐mediated inhibition of STAT3 in liver." (PMID 29285858, 2018). "In the current study, pituitary POMC mRNA expression was completely abolished during experimental sepsis." (PMID 19196477, 2009). "From acute throughout prolonged sepsis, pituitary POMC mRNA was always elevated (all p < 0.05)." (PMID 33593393, 2021). "The two studies of human patients suffering from sepsis revealed that, in the face of the known ACTH–cortisol dissociation, plasma concentrations of the ACTH precursor POMC were substantially elevated from the acute into the prolonged phase of sepsis-induced critical illness." (PMID 33593393, 2021). "Indeed, gene and protein expression of prohormone convertase 1/3, the dominant GR-regulated enzyme responsible for proteolytic cleavage of POMC, was suppressed during all phases of sepsis-induced critical illness." (PMID 33593393, 2021). "Gene expression of the CRH-R, regulator of POMC expression was acutely suppressed (p < 0.0001 for 1-day sepsis group) but increased above normal levels during both subacute and prolonged sepsis (3-day and 7-day sepsis groups, all p < 0.05)." (PMID 33593393, 2021). "To this aim, we employed rat models of sepsis with hypothalamus‐specific POMC knockdown and further tested whether the detrimental impacts of sepsis on liver were diminished." (PMID 29285858, 2018). "With respect to the beneficial effects of leptin administration during sepsis, it is possible to hypothesize that leptin acts on the excitability of the POMC and NPY/AgRP neurons." (PMID 30618812, 2018). "Because α‐MSH could prevent hepatic inflammation through inhibiting the production of related cytokines 32, the increased POMC expression in the hypothalamus might be a compensatory response under the condition of sepsis." (PMID 29285858, 2018). "However, further studies are essential to determine more molecular mechanisms how insulin interacts with POMC neurons to regulate HGP in sepsis." (PMID 29285858, 2018). "Also, from acute throughout prolonged sepsis, pituitary POMC gene expression was elevated." (PMID 33593393, 2021).